TRIM35 (tripartite motif containing 35)
Description:
E3 ubiquitin-protein ligase that participates in multiple biological processes including cell death, glucose metabolism, and in particular, the innate immune response. Mediates 'Lys-63'-linked polyubiquitination of TRAF3 thereby promoting type I interferon production via RIG-I signaling pathway. Can also catalyze 'Lys-48'-linked polyubiquitination and proteasomal degradation of viral proteins such as influenza virus PB2. Acts as a negative feedback regulator of TLR7- and TLR9-triggered signaling. Mechanistically, promotes the 'Lys-48'-linked ubiquitination of IRF7 and induces its degradation via a proteasome-dependent pathway. Reduces FGFR1-dependent tyrosine phosphorylation of PKM, inhibiting PKM-dependent lactate production, glucose metabolism, and cell growth.
Synonyms: HLS5; KIAA1098; MAIR
Tractability: PROTAC: ubiquitination databases record sites on it; its protein half-life has been measured.
Gene: Protein-coding gene on chromosome 8 (27,284,886 to 27,311,289, reverse strand). Ensembl gene ENSG00000104228.
Subcellular location: Cytoplasm; Nucleus
Subcellular location (Human Protein Atlas): Nucleoplasm
Pathways (Reactome):
Immune System: Interferon gamma signaling
Gene Ontology:
Molecular function: ubiquitin protein ligase activity; zinc ion binding
Biological process: antiviral innate immune response; negative regulation of mitotic cell cycle; positive regulation of apoptotic process; suppression of viral release by host; innate immune response; protein ubiquitination
Cellular component: cytoplasm; nucleus
Genetic constraint (gnomAD): Loss-of-function variants: 37 observed, 49.98 expected, observed/expected ratio (o/e) 0.74, 90% interval 0.57 to 0.97. The upper end of that interval is the gene's LOEUF score, 0.97, which puts it in group 4 of 6, group 1 being the genes least tolerant of losing a copy. Missense variants: 648 observed, 708.1 expected, observed/expected ratio (o/e) 0.92, 90% interval 0.86 to 0.98. Synonymous variants: 302 observed, 292.87 expected, observed/expected ratio (o/e) 1.03, 90% interval 0.94 to 1.13.
Homologues: Orthologues: chimpanzee TRIM35 (100% identical), macaque TRIM35 (99% identical), rabbit TRIM35 (94% identical), pig TRIM35 (89% identical), dog TRIM35 (87% identical), guinea pig TRIM35 (84% identical), mouse Trim35 (82% identical), rat Trim35 (82% identical). Paralogues in human: TRIM11 (23% identical), TRIM68 (22% identical), TRIM58 (22% identical), TRIM60 (22% identical), MID1 (22% identical), TRIM4 (22% identical), TRIM69 (22% identical), TRIM72 (22% identical), TRIM39 (21% identical), TRIM41 (21% identical), TRIM75 (21% identical), TRIM27 (21% identical), and 68 more.
Diseases named in the same sentence as TRIM35 in open-access papers:
TRIM35 is named in the same sentence as 19 diseases in open-access papers, as found by Europe PMC text mining. Sharing a sentence is not in itself a finding about the gene and the disease. The quoted sentences say what the papers report.
hepatocellular carcinoma (8 papers, 2015 to 2024). A malignant tumor that arises from hepatocytes. "The TGCA results of ENCORI showed that the expression of TRIM35 was decreased in hepatocellular carcinoma." (PMID 38642184, 2024). "In hepatocellular carcinoma, TRIM35 has been identified as a tumor suppressor by limiting the stability of pyruvate kinase and reducing cellular energetics." (PMID 35482409, 2022). "Trim35 downregulation is a frequent event in hepatocellular carcinoma, and the expression level of Trim35 is negatively correlated with tumor size, histological grade, and serum alpha-fetoprotein concentration." (PMID 34124276, 2021). "Previous report has demonstrated that TRIM35 inhibits the phosphorylation of PKM2 in hepatocellular carcinoma cells and reduces its tumorigenicity." (PMID 32219144, 2020). "In hepatocellular carcinoma (HCC), a newly identified HBV-miRNA (HBV-miR-2) serves as a tumor-suppressor and an oncogenic miRNA by inhibiting Tripartite Motif Containing 35 (TRIM35) and targeting Ras-related nuclear protein (RAN)." (PMID 35889167, 2022). "Further, a previous report has indicated that TRIM35 interacts with PKM2 and suppressed the tumorigenicity in hepatocellular cancer." (PMID 32219144, 2020). "On the other side, tripartite motif-containing protein 35 (TRIM35), identified as a novel tumor suppressor in human hepatocellular carcinoma (HCC), could interact with PKM2 upon the coiled-coil domain." (PMID 29299177, 2017).
viral infection (5 papers, 2020 to 2023). "Deficiency in or inhibition of TRIM35 suppressed the production of type I interferon (IFN) in response to viral infection." (PMID 32562145, 2020). "Several studies have demonstrated that TRIM35 is essential to the host's innate immune response because it can catalyze the ubiquitination process during viral infection." (PMID 36445078, 2022). "E3 ubiquitin-protein ligase TRIM35, which participates in multiple biological processes, including cell death, glucose metabolism, and innate immune response to viral infection, was also found to contain the GIP-9-like motif." (PMID 35629968, 2022). "More TRAF3 protein was immunoprecipitated by the gradually increasing levels of TRIM35 expression across the infection course, indicating TRIM35 interacted with TRAF3 in vivo during natural viral infection." (PMID 32562145, 2020). "Histopathology examination revealed significantly more severe bronchopneumonia with more prominent viral antigen expression in the lungs of Trim35−/− mice compared with Trim35+/+ mice after viral infection." (PMID 32562145, 2020). "Select genes that were highly expressed in COVID-19(+) TV specimens compared to COVID-19(+) PU and COVID-19(-) PU control groups play a central role in regulation of innate immune responses and defense to viral infection, including CARD8, IL1A, CD274, TRIM35, IRF7, and IFIH1." (PMID 37026002, 2023).
lung carcinoma (3 papers, 2020 to 2022). "In summary, our study established TRIM35 as a new tumor-promoting factor in lung cancer and its loss is sufficient to inhibit lung cancer in vivo and in vitro." (PMID 32293015, 2020). "TRIM35 plays a vital role in the tumoral growth of lung cancer and might be a potential diagnostic and prognostic target for patients with lung cancer." (PMID 35371994, 2022). "Finally, our study highlights the potential of TRIM35 as a diagnostic and prognostic marker for lung cancer." (PMID 32293015, 2020). "After this we further validated the effect of TRIM35 on lung cancer cell migration and invasion by scratch and transwell experiments." (PMID 32293015, 2020). "In view of the obvious effect of TRIM35 on the migration and invasion of lung cancer cells, we performed qPCR verification on E-Cad and N-Cad." (PMID 32293015, 2020). "To further determine the effects of TRIM35 on lung cancer cell migration and invasion, we first performed Wound healing assays on A549, H1299, and H460 cells." (PMID 32293015, 2020). "Based on the results of CCK-8 and clone formation, we have seen the significant role played by TRIM35 in lung cancer proliferation." (PMID 32293015, 2020). "We suspect that TRIM35 promotes the migration and invasion of lung cancer cells through the EMT process." (PMID 32293015, 2020). "It was found that TRIM35 was significantly higher in lung cancer cells than HBE cells." (PMID 32293015, 2020). "Finally, we analyzed the expression of TRIM35 in five lung cancer cell lines (A549, H1299, H3122, H460, HCC-827) and normal lung epithelial cells (HBE)." (PMID 32293015, 2020). "The RNA-seq analysis suggested that TRIM35 might promote lung cancer proliferation, migration, and invasion by regulating cancer-associated functions and signaling pathways." (PMID 32293015, 2020). "Hence, we identified TRIM35 played a significant role in tumoral growth and was a potential diagnosis and prognosis target for lung cancer." (PMID 32293015, 2020). "We analyzed the expression of TRIM35 in lung cancer and normal tissues in the Oncomine database." (PMID 32293015, 2020). "During the research, we found TRIM35 promoted the migration and invasion of lung cancer cells." (PMID 32293015, 2020). "Besides, the overexpression of TRIM35 gene could obviously improve the proliferation, migration and invasion ability of lung cancer cells." (PMID 35668376, 2022). "Besides, we analyzed the expression of TRIM35 in lung cancer tissues from 92 patients clinically surgically resected tumor and revealed the relationship between TRIM35 gene expression level and lung cancer pathological type, TNM stage, tumor size, gender, age etc.." (PMID 32293015, 2020). "Furthermore, we analyzed the relationship between TRIM35 expression and prognosis in lung cancer." (PMID 32293015, 2020). "In order to study the mechanism of TRIM35, we found that the expression of TRIM35 in lung cancer and normal tissues were not significantly different by database analysis." (PMID 32293015, 2020).
heart failure (2 papers, 2025). Inability of the heart to pump blood at an adequate rate to meet tissue metabolic requirements. "Moreover, TRIM35 which has been lately confirmed to be involved in heart failure through myocardial cells exhibited a trend toward increased expression within the transplanted EC cluster." (PMID 39865905, 2025).
influenza infection (2 papers, 2020 to 2024). "For instance, TRIM35 mediates the protection against influenza infection by activating TRAF3 and inducing K48-linked ubiquitination and degradation of PB2." (PMID 38498560, 2024).
liver cancer (2 papers, 2020 to 2024). An epithelial or non-epithelial malignant neoplasm that arises from the liver. "TRIM35 suppresses the tumorigenicity of liver cancer cells through the blockade of PKM2/Y105 phosphorylation." (PMID 32293015, 2020). "In the future, HBO may play a role in the treatment of liver cancer by regulating the intervention effect of miR-103a-3p/TRIM35 on hypoxic HCC." (PMID 38642184, 2024).
atherosclerosis (1 paper, 2025). A disease characterized by the build-up of fatty material and calcium deposition in the arterial wall resulting in partial or complete occlusion of the arterial lumen. "TRIM35 expression was indeed obviously elevated in both patients and mice arteries during atherosclerosis and artery remodeling." (PMID 39865905, 2025).
breast carcinoma (1 paper, 2024). "TRIM family E3 ligase TRIM35 was previously shown to mediate the degradation of PKM2 in cardiomyocytes and breast cancer cells." (PMID 39264698, 2024).
H1N1) virus infection (1 paper, 2020). "SiRNA-mediated knockdown of TRIM35 expression increased production of infectious virus by 10-fold; more severe cytopathic effect induced by WSN (H1N1) virus infection was observed in cells that were treated with TRIM35-specific siRNA compared with scrambled siRNA." (PMID 32562145, 2020).
lung adenocarcinoma (1 paper, 2020). A carcinoma that arises from the lung and is characterized by the presence of malignant glandular epithelial cells. "The Oncomine showed that TRIM35 was highly expressed in lung adenocarcinoma (LUAD)." (PMID 32293015, 2020).
tumor (15 papers, 2015 to 2025). "In NSCLC, the E3 ligase TRIM35 acts as a tumor suppressor by inhibiting LSD1’s demethylase activity through K63 ubiquitination at LSD1’s K422 and abrogating assembly of the CoREST complex." (PMID 40479062, 2025). "TRIM35 is a relatively new tumor suppressor, which has been found to have an inhibitory effect in many kinds of tumor cells." (PMID 38642184, 2024). "TRIM35 is a tumor suppressor in HCC but suppresses HCC cell tumorigenicity by blocking PKM2 phosphorylation." (PMID 35371994, 2022). "TRIM35 slows cell growth and triggers apoptosis, both of which are hallmarks of its tumor-suppressing abilities." (PMID 35889167, 2022). "In a genome-wide analysis, TRIM35 was shown as a novel tumor suppressor, and COL4A1 on the 13q34 locus was a frequent amplification target, a finding consistent with our results." (PMID 35814473, 2022). "TRIM35 was originally discovered as a tumor suppressor with the potential to reduce tumor cell proliferation, clonogenicity, and tumorigenicity." (PMID 36445078, 2022). "To explore molecular mediators of the tumor suppressive function of Trim35, we overexpressed Flag-Trim35 in 293FT cells and then performed IP analysis to check the interaction between Trim35 and several clock proteins." (PMID 34124276, 2021). "Compared with that in adjacent normal lymph nodes, nuclear Trim35 immunoreactivity in tumor tissues was markedly lower." (PMID 34124276, 2021). "In conclusion, in the present study, we demonstrated that PKM2 expression was high and TRIM35 expression was low in tumor samples from patients with in HCC." (PMID 25576919, 2015). "The aim of this study was first, to identify the influences of PKM2 and TRIM35 expression on tumor aggressiveness in patients with HCC, and second, to validate these risk factors in patients with early recurrence." (PMID 25576919, 2015). "In a previous study, we identified tripartite motif-containing 35 (TRIM35) as a novel tumor suppressor of hepatic carcinogenesis." (PMID 25576919, 2015). "Thus, TRIM35 exerts both oncogenic and tumor suppressor roles in diverse types of tumors and its role in KIRC requires further exploration." (PMID 35371994, 2022). "Overall, these findings suggest that Trim35 suppresses the progression of DLBCL by modulating the tumor immune microenvironment, indicating that it may be a promising diagnostic and prognostic biomarker in DLBCL." (PMID 34124276, 2021). "And we found overexpressed TRIM35 promoted tumor formation in nude mice in vivo." (PMID 32293015, 2020). "In vivo study further confirmed that overexpression of TRIM35 promoted tumor formation." (PMID 32293015, 2020). "According to previous studies, TRIM35 has both cancer-promoting and tumor-suppressing effects." (PMID 32293015, 2020). "Currently, TRIM35 has been found to act as a tumor-promoting gene in hepatocellular carcinoma and erythroleukemic, and it could regulate erythroid differentiation by modulating GATA-1 activity." (PMID 32293015, 2020). "Tripartite motif-containing 35 (TRIM35) is a tumor suppressor of HCC." (PMID 25576919, 2015). "Previous studies have elucidated that TRIM21, TRIM26, TRIM35, TRIM50, and TRIM56 acted as tumor suppressors by inhibiting tumor cell proliferation, and TRIM3, TRIM16, TRIM21, TRIM25, and TRIM26 negatively regulated migration and invasion in HCC cells." (PMID 35142083, 2022). "We also performed a tissue array to analyze the protein levels of TRIM35 and PKM2 using immunohistochemical staining in 236 HCC tissues, as compared with the levels in matched adjacent non-tumor liver tissues." (PMID 25576919, 2015). "Trim35 is a promising prognostic biomarker in DLBCL, and future studies should be conducted to further uncover the detailed mechanism by which the ubiquitination of clock proteins is related to remodeling of the tumor microenvironment and treatment response." (PMID 34124276, 2021).
tumor (continued). "The expression level of TRIM35 was negatively correlated with the tumor size, histological grade, and AFP concentration (data not shown)." (PMID 25576919, 2015). "Both the negative expression of TRIM35 and the positive expression of PKM2 were associated with poor prognosis and aggressive tumor behavior in cases of HCC." (PMID 25576919, 2015). "Importantly, TRIM35-depleted NSCLC cells could be sensitized to PD-1 blockade through LSD1 inhibitors, which further increase GZMB+CD8+ T cell tumor infiltration." (PMID 40479062, 2025).
cancer (6 papers, 2013 to 2025). A tumor composed of atypical neoplastic, often pleomorphic cells that invade other tissues. "The TRIM35 gene product, also known as hemopoietic lineage switch 5 (HLS5), has been rarely studied with the exception of a report involving in cancer research." (PMID 23555897, 2013). "TRIM35 inhibits phosphorylation of pyruvate kinase isoform M2 (PKM2), which is involved in aerobic glycolysis of cancer cells." (PMID 25576919, 2015). "PKM2/TRIM35 expression could be a biomarker for the prognosis of HCC and target for cancer therapy." (PMID 25576919, 2015).
infection (3 papers, 2020 to 2025). The state of being infected such as from the introduction of a foreign agent such as serum, vaccine, antigenic substance or organism. "In this study, we report that duck TRIM35 (duTRIM35) expression was upregulated upon DTMUV infection in vitro and in vivo, and its expression antagonized DTMUV-induced innate immune responses by targeting duck RIG-I (duRIG-I) in duck embryo fibroblasts." (PMID 36445078, 2022). "We found that the expression of TRIM35 was dramatically induced upon infection with IAV or SeV, or stimulation with poly(I:C), 5′-pppRNA or IFN- IFN-β." (PMID 32562145, 2020). "Upregulation of TRIM35 expression in HEK293 cells led to an approximately 10-fold reduction in virus titer at 48 h post-infection (p.i.)." (PMID 32562145, 2020). "We observed that the expression of Ifnb1 after stimulation with poly(I:C) or 5′-pppRNA or infection with SeV was significantly lower in Trim35−/− macrophages than in Trim35+/+ macrophages." (PMID 32562145, 2020). "In agreement with our observations in mouse peritoneal macrophages, we observed that infection with IAV greatly increased the expression of TRIM35 in A549 and HEK293T cells." (PMID 32562145, 2020). "We found that overexpression of TRIM35 in THP-1 cells significantly enhanced transcription of IFNB1, TNFα, IL6, and ISG56 after infection with SeV." (PMID 32562145, 2020). "Here, we identified TRIM35 (tripartite motif containing 35, also known as HLS5, MAIR) as a positive regulator of the RIG-I-mediated innate immune pathway upon infection with IAV, SeV, or VSV." (PMID 32562145, 2020). "The expression of TRIM35 was dramatically induced after A/WSN/33 (WSN, H1N1) infection compared with that in uninfected control cells." (PMID 32562145, 2020).
TRIM35 also shares sentences with these, for which no sentence is quoted: anemia (1 paper); bronchopneumonia (1); COVID-19 (1); endothelial dysfunction (1); glioma (1); osteosarcoma (1).